MMP10 (matrix metallopeptidase 10)
Diseases named in the same sentence as MMP10 in open-access papers (continued):
Sharing a sentence is not in itself a finding about the gene and the disease.
lung adenocarcinoma (5 papers, 2011 to 2023). A carcinoma that arises from the lung and is characterized by the presence of malignant glandular epithelial cells. "As we showed in our study, MMP1, MMP9 and MMP10 genes are elevated in human lung adenocarcinomas relative to normal tissue." (PMID 30988374, 2019). "Cultures enriched in CSCs from mouse lung adenocarcinoma cells express elevated Mmp10, Nanog, Aldh1, CD133, Notch3, Notch4, Hey1 and Hey2." (PMID 22545096, 2012). "Here we show that Mmp10 is overexpressed in CSC-enriched oncosphere cultures from two mouse lung adenocarcinoma cell lines and is required for enhanced transformed growth and clonal expansion in vitro, and for tumor initiation in vivo." (PMID 22545096, 2012). "Not only is Mmp10 elevated in tumors developed in two different mouse models of Kras-induced lung adenocarcinoma, genetic knock out of Mmp10 leads to formation of significantly fewer tumors, suggesting an effect of Mmp10 on tumor initiation." (PMID 22022614, 2011). "We recently identified Mmp10 as a gene that is highly induced in tumor-initiating lung bronchioalveolar stem cells (BASCs) upon activation of oncogenic Kras in a mouse model of lung adenocarcinoma." (PMID 22022614, 2011). "Our expression profiling data of human tumors demonstrates a close functional link between CSC, Mmp10 expression and metastatic potential, suggesting that Mmp10 plays a similar role in human lung adenocarcinoma CSC invasion and metastasis." (PMID 22022614, 2011). "High MMP10 levels in specimens of lung adenocarcinoma were related to poor patient outcomes." (PMID 36908704, 2023). "Interestingly, Mmp10 has previously been reported as required for lung stem cell expansion as well as lung adenocarcinoma initiation and metastasis, making it a logical candidate to mediate the TPC phenotypes regulated by G9a." (PMID 30455465, 2018). "In order to determine whether Mmp10 is involved in lung tumor formation, mice were treated with the smoke carcinogen urethane to induce lung adenocarcinoma tumors using well-established protocols." (PMID 22022614, 2011). "Similarly to rescued shG9a adenocarcinoma cells, we observed significant downregulation of the G9a targets Sca-1 and Mmp10, suggesting that Kdm3a depletion may impede TPCs through the same mechanisms as G9a expression in lung adenocarcinoma cells." (PMID 30455465, 2018). "Further studies will be required to determine whether Mmp10 promotes metastasis and chemoresistance in human tumor cells by maintaining a highly metastatic, chemoresistant cancer stem cell population, as our present data in mouse lung adenocarcinoma cells would predict." (PMID 22545096, 2012). "For this purpose, we divided a publicly-available dataset consisting of genome-wide expression analysis of human lung adenocarcinomas (GSE11969) into two equal sized groups of 30 samples comprised of the tumors with the highest (High) and lowest (Low) Mmp10 RNA expression, respectively." (PMID 22022614, 2011).
lymph node metastasis (5 papers, 2011 to 2024). "In cervical squamous cell carcinoma and tongue squamous cell cancer, MMP10 was shown to be positively correlated with lymph node metastasis." (PMID 38374122, 2024). "Specifically, real-time PCR and IHC data reveal MMP10 overexpression in 58/66 (88%) and 10/13 (77%), and low expression in 8/66 (12%) and 3/13 (23%) of patients with lymph node metastasis, respectively." (PMID 36650344, 2023). "Then, we compared the MMP-10 expression with invasion pattern, stage grouping and lymph node metastasis." (PMID 21998657, 2011). "Positive H. pylori infection and positive expression of MMP-1 and MMP-10 were associated with lymph node metastasis and clinical stage (P<0.05), but not with age, gender or differentiation degree (P>0.05)." (PMID 25120597, 2014). "In addition, MMP-10 expression was significantly correlated with lymph node metastasis (P<0.001)." (PMID 21998657, 2011). "Twenty-nine of 89 HNSCC cases with high expression of MMP-10 had lymph node metastasis, while 5 of 27 HNSCC cases with low expression of MMP-10 had lymph node metastasis." (PMID 21998657, 2011).
lymphoma (5 papers, 2005 to 2016). A malignant (clonal) proliferation of B- lymphocytes or T- lymphocytes which involves the lymph nodes, bone marrow and/or extranodal sites. "Overexpression of MMP10 in transfected lymphoma cells has been shown to stimulate invasive activity in vitro and promote thymic lymphoma growth in an in vivo murine model." (PMID 16168081, 2005). "IL10 knockout experiments in mice have previously underlined its role in B1 cell expansion and development of CLL, whereas Mmp10 is potentially a novel CLL gene, which is known to be induced in lymphoma cells thereby accelerating the tumor growth." (PMID 27533467, 2016).
metastatic tumors (5 papers, 2015 to 2023). "However, key MMP remodeling-associated genes PLAU and MMP10 and basal cell marker KRT19 were uniquely shared upregulated genes in metastatic tumors (MET and PRI+)." (PMID 35480116, 2022). "The highest differentially expressed genes in metastatic (MET and PRI+) versus non-metastatic tumors (PRI-) and SES included PLAU, PLAUR, MMP1, MMP10, MMP13, ITGA5, VEGFA, and various inflammatory cytokine genes." (PMID 35480116, 2022). "Our results indicate that MMP10 is differentially expressed in primary CRC, recurrent tumors, and metastatic tumors compared to normal tissue." (PMID 35432477, 2022). "MMP7, MMP13, and MMP10 were upregulated in metastatic tumours compared with nonmetastatic tumours." (PMID 31996191, 2020). "MMP7, MMP13, and MMP10 were upregulated, and MMP12 and MMP9 were downregulated in metastatic tumours compared with nonmetastatic tumours." (PMID 31996191, 2020).
muscular dystrophy (5 papers, 2014 to 2023). Muscular dystrophy (MD) refers to a group of more than 30 genetic diseases characterized by progressive weakness and degeneration of the skeletal muscles that control movement. "MMP-10 deficiency has been linked with the progression of severe muscular dystrophy in aged dystrophic mice." (PMID 36289739, 2022). "Here, we aimed to investigate the involvement of MMP-10 in the progression of severe muscular dystrophy and to characterize MMP-10 loss in skeletal and cardiac muscles of aged dystrophic mice." (PMID 34947929, 2021). "Matrix metalloproteinases (MMPs) have been implicated in the progression of muscular dystrophy, and recent studies have reported the role of MMP-10 in skeletal muscle pathology of young dystrophic mice." (PMID 34947929, 2021). "Our findings indicate that MMP-10 is implicated in severe muscular dystrophy progression, thus identifying a new area of research that could lead to future therapies for dystrophic muscles." (PMID 34947929, 2021). "Nevertheless, the inflammatory response disrupts heart homeostasis, and the degree of inflammatory cell infiltration in cardiac tissue is strongly associated with disease severity in muscular dystrophies, supporting our finding that MMP-10 loss led to severe dystrophic phenotype." (PMID 34947929, 2021). "Significantly, the effect of MMP-10 on satellite cell aging can be extended to another context of muscle wasting, muscular dystrophy." (PMID 37228645, 2023). "Now, we further addressed the participation of MMP-10 in muscular dystrophy progression by extending our previous data to aged animals." (PMID 34947929, 2021). "We analyzed the skeletal and cardiac muscles of aged mdx mice, which reproduce more accurately human disease, to assess the involvement of MMP-10 in severe muscular dystrophy." (PMID 34947929, 2021). "To assess the role of MMP-10 in severe muscular dystrophy, we analyzed the consequences of MMP-10 ablation in aged mdx mice." (PMID 34947929, 2021). "Due to the critical role that MMP-10 plays during muscular dystrophy progression and the consequences of MMPs deregulation during cardiac remodeling, we aimed to better understand the biological function of MMP-10 in dystrophic mice." (PMID 34947929, 2021). "To this end, we histologically analyzed skeletal and cardiac muscles of aged mdx mice to assess the implication of MMP-10 ablation in severe muscular dystrophy." (PMID 34947929, 2021). "MMP-10 is known to be involved in bone growth but has also been shown to be involved in tissue repair processes and specifically in muscular dystrophy mouse models." (PMID 31754018, 2020). "Selected genes from this array were validated by immunohistochemistry (IHC) to confirm the presence of IGF-1, BMPR1b and MMP-10 proteins in tibial sections from WT and muscular dystrophy mice." (PMID 31754018, 2020). "This analysis was limited to bone from 7-week-old mice and revealed a 2- to 3.75-fold upregulation of matrix metalloprotease 10 (Mmp10) and bone morphogenetic protein receptor type 1b (Bmpr1b) in all muscular dystrophy models compared to WT mice." (PMID 31754018, 2020). "We found that all the muscular dystrophy models have an upregulation of Mmp10 and Bmpr1b gene expression compared to WT mice." (PMID 31754018, 2020). "To address the participation of MMP-10 in severe muscular dystrophy, we examined by immunostaining the MMP-10 protein levels in hearts from young and aged wild-type and mdx mice, finding that its abundance significantly increased during physiological aging and disease progression." (PMID 34947929, 2021). "MMP-10 and BMPR1b were chosen because they were upregulated in all muscular dystrophy mouse models." (PMID 31754018, 2020). "While MMPIs have been found to mitigate disease progression in mouse models, genetic studies have provided evidence that some MMPs (e.g., MMP-2 and MMP-10) may have beneficial roles in muscular dystrophy." (PMID 25364719, 2014).
muscular dystrophy (continued). "Thus, we considered that MMP-10 might be beneficial in a context of impaired muscle regeneration such as muscular dystrophy, where satellite cells are unable to appropriately maintain the muscle repair response." (PMID 37228645, 2023). "In order to evaluate the implications of MMP-10 in serious muscular dystrophy, mdx mice lacking MMP-10 were left to age." (PMID 34947929, 2021).
type 2 diabetes (5 papers, 2020 to 2025). "In our cross-sectional analysis of individuals with type 2 diabetes from three different cohorts, a multiplex proteomics assay identified four circulating proteins associated with DKD: KIM-1, GDF-15, myoglobin, and MMP-10." (PMID 31805809, 2020). "Aim: to assess how vitD3 status is related to MMP-10 levels in patients with Type 2 diabetes (T2D)." (PMID 36079742, 2022). "In patients with Type 2 diabetes (T2D) and CKD, elevated serum MMP-10 values were observed at early stages of nephropathy, followed by a progressive increase at more advanced CKD stages." (PMID 36079742, 2022). "A final group of five biomarkers (CXCL9, IL-2RB, MMP-10, STAMBP, TNF-α) showed positive associations with changes in CES-D in people with type 2 diabetes but without significant effect modification (pinteraction ≤ 0.18)." (PMID 40624224, 2025). "MMP-10 and TIMP-1 are increased from the early stages of type 2 diabetes." (PMID 31913319, 2020). "MMP-10 and TIMP-1 have been implicated in T1DM however, to the best of our knowledge, no previous studies have analysed the role of MMP-10 in type 2 diabetes (T2DM), while TIMP-1 data is not conclusive." (PMID 31913319, 2020).
bladder tumor (4 papers, 2014 to 2022). "Only one small study has previously reported the expression of MMP-10 in human bladder tumors." (PMID 24885595, 2014).
cervical carcinoma (4 papers, 2014 to 2025). A carcinoma arising from either the exocervical squamous epithelium or the endocervical glandular epithelium. "MMP-7 and MMP-10 not only differentiate cervical cancer from dysplasia and healthy controls but also reflect disease stage, supporting their potential clinical application as sensitive and specific serum biomarkers." (PMID 41462922, 2025). "MMP-7 and MMP-10 showed the most pronounced increases in cervical cancer patients, with median concentrations rising progressively from cervical dysplasia to early-stage (I–II) and advanced-stage (III–IV) cancer." (PMID 41462922, 2025). "Lastly, we demonstrate that targeting MMP-10 in a human cervical cancer xenograft model with siRNA inhibited angiogenesis and induced apoptosis, resulting in a significant reduction in the growth of xenograft tumors." (PMID 24885595, 2014). "Here, we are the first to report the relative increased expression of MMP-10 in human cervical cancer compared to benign tissue, and that expression correlates with the invasive phenotype of malignant cervical tumors." (PMID 24885595, 2014). "We monitored MMP-10 protein expression in a panel of human cervical cancer tissues by immunohistochemical staining of a commercial TMA comprised of 10 benign specimens and 70 cancer tissues." (PMID 24885595, 2014). "Furthermore, MMP10 has been shown to be highly expressed in breast, prostate, and cervical cancer." (PMID 24999452, 2014). "Here, we utilized two human cell lines for experimental perturbation of MMP-10; the benign SV40 transformed urothelial line UROtsa and the cervical cancer cell line HeLa." (PMID 24885595, 2014). "In the case of MMP-10, there are no available studies describing the diagnostic usefulness of this MMP in cervical cancer; therefore, our study is innovative." (PMID 41462922, 2025). "In the HeLa cervical cancer cell line, MMP-10 was not expressed in culture." (PMID 24885595, 2014).
esophageal squamous cell carcinoma (4 papers, 2016 to 2024). Esophageal squamous cell carcinoma (ESCC) is a type of esophageal carcinoma (EC) that can affect any part of the esophagus, but is usually located in the upper or middle third. "AJUBA promotes the migration and invasion of esophageal squamous cell carcinoma cells (ESCC) through the up-regulation of matrix metalloproteinase 10 (MMP10) and MMP13 expression in ESCC." (PMID 31262974, 2019). "Furthermore, NSUN2-mediated lncRNA NMR promotes tumor progression by controlling the expression of important oncogenic drivers in esophageal squamous cell carcinoma, such as matrix metalloproteinase 10 (MMP10) and MMP3." (PMID 38351139, 2024). "In esophageal squamous cell carcinoma (ESCC), lncRNA NMR methylated by NSUN2 combines with the chromatin regulator BPTF to promote the expression of MMP3 and MMP10 via the ERK1/2 pathway; thus, promoting the progression of ESCC." (PMID 34777473, 2021).
gastritis (4 papers, 2014 to 2025). Inflammation of the stomach. "The negative correlations with antioxidant enzymes (CAT and GPX) indicate that the depletion of the antioxidant defense system contributes to ERK/MMP-10, signaling activation during gastritis." (PMID 41302134, 2025). "The effect of MMP-10 is paradoxical, which involves promoting gastritis and H. pylori proliferation." (PMID 32411209, 2020).
glioblastoma (4 papers, 2013 to 2024). The most malignant astrocytic tumor (WHO grade IV). "The fact that CFM-4 treatment of Daoy cells resulted in a 2-fold down-regulation of MMP10, and that the activities of MMPs were found to be associated with glioblastoma and MB cell invasiveness, we determined whether and to what extent exposure to CFMs resulted in reduced activities of various MMPs." (PMID 23826121, 2013). "In our case, we unequivocally confirmed the negative expression of both MMPs at the gene level, which, in the case of MMP10, was also of significance for the group of astrocytomas and glioblastomas." (PMID 38474106, 2024). "A statistically significant reduction in mRNA levels of MMP10 in glioblastomas (p < 0.05) and astrocytomas (p = 0.022) compared to the control group was recorded." (PMID 38474106, 2024). "Notably, patients with glioblastomas exhibited almost consistently elevated protein levels compared to the other groups, except for MMP10 and TIMP2." (PMID 38474106, 2024). "Furthermore, a number of studies have found that MMP-10 is expressed in human glioblastoma, and oral, esophageal, stomach, colon, colorectal and liver cancer, as well as other malignant cells." (PMID 25009646, 2014). "Overall, changes in fold regulation with statistical significance were recorded for MMP3 (p < 0.001), MMP10 (p < 0.001), and TIMP2 (p < 0.05) in glioblastoma." (PMID 38474106, 2024). "There, genes with a higher expression in glioblastoma compared to astrocytoma were VEGFA, 4EBP1, CCL2, PLAU (uPA), CXCL8 (IL8), CXCL10 (IP10), CASP8, HGF, LIF, CD40, CDCp1, TNFRSF11B (OPG), CD274 (PD-L1), IL6, CXCL1, CCL20 (MIP3α), CCL8 (MCP2), CD244, MMP1, TNFRSF9, CXCL6, MMP10, FGF5)." (PMID 35301393, 2022).
ischemic stroke (4 papers, 2013 to 2022). A stroke disorder caused by obstruction of blood flow to the brain, due to thrombotic (local blood clot formation) or embolic (due to a blood clot or other material traveling from another site) event. "The findings in respect to MMP-10 are in consonance with a previous study showing an association between serum MMP-10 and functional outcome in ischemic stroke patients; however, in our current study, we found for the first time higher serum MMP-10 in non-surviving than in surviving MMCAI patients." (PMID 26162891, 2015). "Neither of the studied circulating parameters (VWFAc, MMP10, and TAFIa) were associated with mortality after ischemic stroke in our cohort nor with stroke TOAST subtypes (data not shown)." (PMID 33692737, 2021). "However the prognostic value of circulating levels of TIMP-1 and MMP-10 in functional outcome of ischemic stroke patients has been scarcely studied." (PMID 26162891, 2015). "However the prognostic value of circulating levels of tissue inhibitor of matrix metalloproteinases (TIMP)-1 and MMP-10 in functional outcome of ischemic stroke patients has been scarcely studied." (PMID 26162891, 2015). "In addition to MMP-2/-3/-9, MMP-10 (stromelysin-2) may also play an active role in mediating BBB disruption during ischemic stroke." (PMID 23565108, 2013). "Previously there were found higher circulating levels of MMP-9 and MMP-10 and TIMP-1 in ischemic stroke patients than in controls." (PMID 26162891, 2015). "The effect of MMP-10 on fibrinolysis was studied in vitro and in vivo in MMP-10 KO mice using two different murine models of arterial thrombosis, laser-induced carotid injury and ischemic stroke." (PMID 23565108, 2013).
pancreatic adenocarcinoma (4 papers, 2016 to 2021). "In fact, MEF2C was proposed to promote metastases development in pancreatic adenocarcinoma by inducing metalloproteinase (MMP) 10 transcription and to promote myeloid leukaemia, behaving as an oncogene by cooperating with the Sox4 gene." (PMID 33673112, 2021). "MEF2C has recently been proposed as a new oncogene, promoting metastasis in pancreatic adenocarcinoma by inducing MMP10 transcription and mediating VEGF induction of vasculogenic mimicry, migration, and invasion in hepatocellular carcinoma." (PMID 31930767, 2020). "A role for MMP10 downstream of ErbB2 has been also demonstrated in pancreatic adenocarcinoma." (PMID 27351228, 2016). "Furthermore, higher MMP10 histoscores correlated with higher pancreatic adenocarcinoma grades." (PMID 28031255, 2017).
pancreatic ductal adenocarcinoma (4 papers, 2014 to 2024). An infiltrating adenocarcinoma that arises from the epithelial cells of the pancreas. "However, YY1 mitigates pancreatic ductal adenocarcinoma metastasis by suppressing MMP10 transcription." (PMID 38351178, 2024). "Therefore, we presume that YY1 suppresses invasion and metastasis of pancreatic ductal adenocarcinoma by downregulating MMP10 in a MUC4/ErbB2/MEF2C-dependent mechanism." (PMID 24884523, 2014).